FOXC2 (forkhead box C2)
Diseases named in the same sentence as FOXC2 in open-access papers (continued):
Sharing a sentence is not in itself a finding about the gene and the disease.
breast carcinoma (continued). "FoxC2, a member of the Forkhead box family of transcription factors, is involved in EMT induction and the metastatic ability of breast cancer cells." (PMID 26797644, 2016). "Microarray analysis of the invasive breast cancer tissue showed increased expression of GLI1 and forkhead box C2 (FOXC2), a transcription factor involved in embryonic development and tissue homeostasis." (PMID 26633513, 2015). "FOXC1, FOXC2, and FOXQ1 are highly expressed in basal-like subtype breast cancer, but are less present in luminal subtype cancer." (PMID 25848863, 2015). "It has been reported that stem cells from human mammary glands and mammary carcinomas express EMT markers including increased vimentin, SLUG and FOXC2 gene expression and decreased E-cadherin expression." (PMID 20027313, 2009). "Mesenchyme Forkhead 1 (FOXC2) which induced by Twist, Snail, Goosecoid and TGF-β1 plays a central role in promoting invasion and metastasis in human basal-like breast cancers." (PMID 20025748, 2009). "Therefore, this study aims to investigate the expression patterns and potential regulatory relationships between key transcription factors (FOXC2, SNAIL, and ZEB) and oncogenic lncRNAs (HOTAIR, MALAT1, and UCA1) in metastatic breast cancer stem cells." (PMID 40781106, 2025). "Using E/M (CD104highCD44high) and M (CD104low CD44high) subpopulations isolated from MDA-MB-468 and HCC1143 basal-like breast cancer cell lines, we uncovered an upregulation of TCF1 and FOXC2 in E/M relative to M cells, which was in turn able to convert M into E/M cells." (PMID 40764669, 2025). "Like FOXC2 and SNAIL, ZEB factors represent important transcription factors that may interact with lncRNA networks in breast cancer progression, particularly in maintaining cancer stem cell properties and therapeutic resistance." (PMID 40781106, 2025). "Further analysis of our breast cancer PDTXs revealed enrichment of Bev resistance genes in human, but not mouse, genes that correlate with human FOXC2-targets, suggesting that the Bevacizumab resistance gene signature is of tumor origin." (PMID 37499655, 2023). "The FOXC2 is a type of FOX transcription factor, and its increased expression is an independent prognostic factor in several cancers, including NSCLC (non-small-cell lung cancer), cancer of breast, esophagus, colorectal, and that of the stomach." (PMID 32508532, 2020). "FOXC2 has been reported to be overexpressed in numerous cancers and function as a central regulator for epithelia-mesenchymal transition (EMT) and metastasis, including breast cancer, lung cancer, colorectal cancer, et al19-22." (PMID 31367258, 2019). "FOXC2 has been introduced as a mediator of mesenchymal differentiation in the course of EMT, downstream of TGFβ and other EMT‐regulators, and identified as a decisive factor for carcinoma dissemination in breast cancer models." (PMID 31464093, 2019). "Second, six genes, CHI3L1, CXCL8, FOXC2, SERPINE1, SFRP2, and TF, which are grouped within the highest enrichment GO term, “positive regulation of angiogenesis”, have been reported to play roles in various cancer processes, including breast cancer." (PMID 30205506, 2018). "We examined the expression pattern of PKCα and FOXC2 in ER+ and TNBC breast cancer cell lines." (PMID 29216867, 2017). "Accordingly, we detected a significant enrichment of FOXC2 occupancy on the p120-catenin promoter in all cell lines representing either endocrine resistant or basal A breast cancer subtypes, but not in endocrine sensitive MCF7." (PMID 29216867, 2017). "Furthermore, an in vitro study demonstrated that FoxC2 lies at the crossroads of EMT and cancer stem cell properties in breast cancer." (PMID 26758745, 2016). "Similar to NUMB, the EMT negative regulators GATA3 and FOXA1 had significantly lower expression in the BLBC subtypes, ER-negative and higher histological grade breast cancer patients, while the EMT inducers FOXC1, FOXC2 and SNAI1 mimicked the expression profiles of Notch1." (PMID 27506933, 2016).
breast carcinoma (continued). "In breast cancer, PI3K is activated down-stream of Her2 and other signalling pathways and this may have implications for FoxC2 induction and EMT promotion." (PMID 26797644, 2016). "Similar to NUMB, the EMT negative regulators GATA3 and FOXA1 had significantly lower expression in the BLBC subtypes and in ER-negative and higher histological grade breast cancer patients, whereas the EMT inducers FOXC1, FOXC2 and SNAI1 mimicked the expression profile of Notch1." (PMID 27506933, 2016). "It has been shown that co-culturing mature adipocytes with breast cancer (BC) cells enhances cancer cell growth and EMT by increasing the expression of FOXC2, TWIST1, and N-cadherin." (PMID 39201656, 2024). "Indeed, FOXC2 suppression may inhibit EMT induction and multidrug resistance in basal-like breast cancer and nasopharyngeal cancer." (PMID 29801468, 2018). "Thus, we speculate that coincident expression of FOXC2 and FOXM1 in basal-like breast cancer cells contributes to both the maintenance and self-renewal of carcinoma cells undergoing a partial EMT, thereby supporting the stemness and aggressiveness of the TNBC subtype." (PMID 40764669, 2025). "Whereas FOXC2 was previously demonstrated to be a repressor of p120-catenin expression in lung cancer, it is not known whether this inverse relationship holds true in breast cancer." (PMID 29216867, 2017). "In conclusion, our findings demonstrate that metastatic breast cancer stem cells exhibit selective rather than widespread gene expression changes, with SNAIL and FOXC2 emerging as key molecular drivers." (PMID 40781106, 2025).
lymphedema (54 papers, 2007 to 2025). Excess fluid collection in tissues, causing swelling. "Mutations in the GATA2 gene, the transcription factor controlling Prox1 and FOXC2 expression, cause primary lymphedema with myelodysplasia." (PMID 40766782, 2025). "Heterozygous loss-of-function mutations in FOXC2 are associated with lymphedema-distichiasis syndrome (LDS)." (PMID 40553105, 2025). "The impact of loss of Erg and Fli1 function on lymphatic development in mice is consistent with FOXC2 mutations in lymphedema-distichiasis syndrome or ERG gene variants underlying primary lymphedema in humans." (PMID 41460562, 2025). "Levels of FOXC2, which is linked to primary venous valve failure and lymphedema when mutated, also increase from valvular to lymphatic ECs (Moran’s I = 0.49)." (PMID 38206912, 2024). "Inactivating mutations in FOXC2 are the underlying cause of lymphedema-distichiasis syndrome (LD; OMIM 153400) characterized by late-onset hereditary lymphedema and the presence of a double row of eyelashes (distichiasis)." (PMID 37407839, 2023). "Subsequent activation of Forkhead box protein C2 (FOXC2), a lymphedema-associated transcription factor, downstream of this pathway promotes lymphatic vessel patterning in mice." (PMID 36672254, 2023). "More importantly, ablation of Foxo1 in a mouse model for human disease lymphedema–distichiasis, the Foxc2 heterozygous mice, completely resolves both the loss of valves and the leakiness of valves in this disease model." (PMID 36742198, 2022). "In particular, mutations in SOX18, PROX1, GATA2, and FOXC2 cause various forms of syndromic lymphedema." (PMID 35806420, 2022). "For example, heterozygosity of the FOXC2 gene causes lymphedema-distichiasis syndrome in human patients." (PMID 36742198, 2022). "Although Foxc2-null animals are embryonically lethal, the Foxc2 heterozygous mice are a model of the human disease lymphedema-distichiasis with severe lymphatic valve loss." (PMID 36742198, 2022). "For example, Sox18 and Foxc2 mutations in humans cause hypotrichosis-lymphoedema-telangiectasia and lymphedema-distichiasis, respectively." (PMID 32882780, 2021). "Despite their overlapping function, loss of Foxc2 alone leads to lymphatic valve defects in mouse embryos, while mutations in human FOXC2 are associated with lymphedema." (PMID 34716915, 2021). "There are currently five genes known to be associated with late-onset lymphoedema: FOXC2,27GJC2,28 29GATA2,30HGF31 and CELSR132." (PMID 32409509, 2020). "This study concluded that the GATA2 mutations abolishing enhancer-binding resulted in the loss of valves due to reduced expression of PROX1 and FOXC2, and strongly suggests that a loss of valves leads to lymphedema in human patients." (PMID 32824219, 2020). "In conclusion, our functional studies further highlighted the different molecular consequences of some FOXC2 mutations identified in families with lymphedema-distichiasis." (PMID 32698337, 2020). "Dominant heterozygous mutations in the forkhead family transcription factor FOXC2 are associated with human lymphedema, venous insufficiency and varicose veins." (PMID 29125824, 2017). "Recently, lymphedema patients with FOXC2 mutations were also found to possess fewer VVs, and those present had shorter leaflets." (PMID 29125824, 2017). "Dominant mutations in the FOXC2 gene (MIM 602402), coding for the forkhead transcription factor FOXC2, cause a form of lymphedema with variable age of onset (range: 7-40 years), often associated with distichiasis." (PMID 27276711, 2016). "Our data reveal that either a complete loss or a significant gain of FOXC2 function can cause a perturbation of lymphatic vessel formation leading to lymphedema." (PMID 27276711, 2016). "In turn, Wnt/β-catenin signaling controls the expression of several molecules, including the lymphedema-associated transcription factor FOXC2." (PMID 27313318, 2016).
lymphedema (continued). "In conclusion, we have analyzed the molecular consequence of FOXC2 mutations identified in six Italian families with lymphedema-distichiasis, providing evidences of patients with inactivating versus activating mutations of the FOXC2 transcription factor." (PMID 27276711, 2016). "Dominant mutations in the FOXC2 gene cause a form of lymphedema primarily of the limbs that usually develops at or after puberty." (PMID 27276711, 2016). "Mutations in the Foxc2 gene cause lymphedema-distichiasis, a human disease with severe lymphedema and double rows of eyelashes." (PMID 26327394, 2015). "While FOXC2 mutations were found in a total of 13 subjects, lymphedema was found in 4 and distichiasis in 9 subjects." (PMID 24278289, 2013). "The presentation of Lymphedema-Distischiasis (LD, OMIM153400), a hereditary form of lymphedema, is due to the loss of the transcription factor FoxC2." (PMID 23341894, 2013). "Mutations of the FOXC2 gene cause lymphedema-distichiasis syndrome - characterised by double rows of eyelashes, ptosis, photophobia and anterior segment anomalies reminiscent of those caused by FOXC1." (PMID 22022403, 2011). "Lymphedema-distichiasis is linked to the forkhead transrciption factor FOXC2, and the lymphedema-hypotrichosis-telangiectasia syndrome is caused by mutations in the transcription factor SOX18." (PMID 17584927, 2007). "Moreover, Foxo1 ablation in Foxc2 heterozygous mice, the model of human lymphedema-distichiasis disease, rescues both the valve loss and valve dysfunction to the wildtype level." (PMID 36742198, 2022). "Therefore, in addition to Foxo1 deletion, moderately increased β-catenin activity can rescue the valve loss in Foxc2 heterozygous mice, the mouse model for lymphedema-distichiasis." (PMID 36742198, 2022). "The late onset lymphedema is mainly associated with distichiasis syndrome (FOXC2 mutation)." (PMID 33573286, 2021). "One had a de novo mutation (lymphedema–distichiasis syndrome, FOXC2)." (PMID 33897756, 2021). "Mutations in the transcription factor FOXC2 are predominately associated with lymphedema." (PMID 32510325, 2020). "FoxC2 point mutations in humans cause a rare genetic multisystem disorder called lymphedema-distichiasis syndrome, which is characterized by the development of extra eyelashes, functionally defective lymphatic valves and presence of lymphedema." (PMID 30979062, 2019). "Moreover, it was noted that the craniofacial, cardiovascular, and skeletal abnormalities sometimes associated with lymphedema-distichiasis syndrome in humans, had previously been shown to be fully penetrant in homozygous FOXC2-null mice." (PMID 27276711, 2016). "VEGF-C, neuropilin-2, and FOXC2 polymorphisms have been identified in patients with breast cancer-related lymphedema (BCRL), suggesting that baseline differences in VEGFR3 activation or lymphatic function may contribute to the risk of developing post-surgical lymphedema." (PMID 38201272, 2023). "Interestingly, mutations in Foxc2 result in lymphedema-distichiasis syndrome in humans." (PMID 34072103, 2021). "Therefore, the presence of a higher amount of FOXC2 molecules might temporarily compensate for transcriptional activity impairment in females carrying FOXC2 mutations, delaying lymphedema onset." (PMID 33925370, 2021). "Additionally, the mutations in GATA2 that underlie Emberger syndrome produced mutant GATA2 proteins that were unable to bind enhancer elements in both the PROX1 and FOXC2 genes that were active only in the valve cells, and only these mutations were associated with lymphedema in patients." (PMID 32824219, 2020). "We therefore performed functional characterization of FOXC2 mutations located in different protein domains to provide novel information on structure-function relationships of the FOXC2 transcription factor and to get further insight into the disease-causing mechanism of lymphedema." (PMID 27276711, 2016).
lymphedema (continued). "Despite the great importance of the FOXC2 transcription factor in human pathophysiology and the increasing number of different mutations identified in patients with lymphedema, the molecular consequences caused by FOXC2 gene variations are almost entirely unknown." (PMID 27276711, 2016). "This disruption leads to congenital lymphatic dysfunction and lymphedema through the regulation of Foxc2 (Forkhead Box C2) a member of forkhead family of transcription factors which may play a role in the development of mesenchymal tissues and that is associated with lymphedema development." (PMID 39800748, 2025). "Primary lymphedema can be an indicator of various complex hereditary syndromes, such as Noonan syndrome (associated with the PTPN11 gene), lymphedema–distichiasis syndrome (FOXC2), and hypotrichosis–lymphedema–telangiectasia syndrome (SOX18)." (PMID 38791500, 2024). "Dysregulation of FOXC2 expression has also been found to promote defects in lymphatic remodeling and hyperplastic lymphedema-distichiasis (LD)." (PMID 39473610, 2024). "Murine heterozygous Foxc2 genetic knockdowns have been previously been used as a model for human lymphedema-distichiasis and demonstrate similar phenotypic symptoms, including hyperplasia of lymphatics and lymph nodes." (PMID 39473610, 2024). "Genetic predisposition of lymphatic dysfunction results in primary lymphedema such as genes pertaining to lymphagiogenesis (VEGFR3, FOXC2, SOX18, ITGA9 and etc.)are the influencing factor of primary lymphedema in defective form." (PMID 37986071, 2023). "Previous evidence described the genetic screening of hereditary syndromes accompanied by the genetic mutations in genes such as FOXC2, FLT-4, and SOX18 for lymphedema-distichiasis, Milroy disease, and hypotrichosis-lymphedema-telangiectasia, respectively." (PMID 37267206, 2023). "To further investigate the function of nuclear β-catenin in vivo, we genetically increased the activity of β-catenin in the nucleus of LECs in Foxc2 heterozygous mice, a mouse model of lymphedema-distichiasis." (PMID 36742198, 2022). "Foxc2 heterozygous mice have been characterized as the mouse model for human lymphedema-distichiasis disease." (PMID 36742198, 2022). "Lymphovenous valve insufficiency is a feature of several lymphedema mouse models with disruptions in genes including Prox1, Foxc2, Cx37, Gata2, Pdpn, or Clec2." (PMID 34055805, 2021). "Similar to humans, FoxC2 haploinsufficient mice exhibit lymph node hyperplasia and lymphedema of hind limbs and display distichiasis." (PMID 30979062, 2019). "Functionally, FOXC2, also known as mesenchyme forkhead 1, is known as an important regulator of lymphangiogenesis, and FOXC2-knockout mice display a lymphedema-distichiasis syndrome." (PMID 29801468, 2018). "Foxc2+/− mice, which are models for lymphedema-distichiasis syndrome, display retrograde lymph flow, possibly because they have incompetent LVs." (PMID 29125824, 2017). "Four among 13 subjects with FOXC2 mutations presented with SEDAC alone and only 3 subjects with SEDAC had both of the 2 major features of LDS (lymphedema and distichiasis)." (PMID 24278289, 2013). "The familial cases with FOXC2 mutations were also diagnosed as LDS, since the family members had lymphedema and/or distichiasis." (PMID 24278289, 2013). "Importantly, Foxc2+/− mice, a model for lymphedema-distichiasis syndrome, also develop TLOs in the terminal ileum." (PMID 40553105, 2025). "Kanady and colleagues generated Foxc2+/−Cx37−/− mice and observed that these mice typically die perinatally and suffer from generalized lymphedema in utero, craniofacial abnormalities, severe dilation of intestinal lymphatics, abnormal lacteal development and lack of lymphatic valves." (PMID 34072103, 2021). "The majority of FOXC2 mutations linked to lymphedema-distichiasis syndrome are insertion/deletion (73%) and nonsense mutations (10%)." (PMID 32698337, 2020).